U3 (Small nucleolar RNA U3 )
Synonyms: LOC124904154
Gene: Small nucleolar RNA gene on chromosome 17 (58,631,641 to 58,631,836, reverse strand). Ensembl gene ENSG00000212195.
Gene Ontology:
Biological process: RNA processing
Cellular component: nucleolus
Homologues: Orthologues: macaque U3 (70% identical). Paralogues in human: SNORD3D (70% identical), SNORD3H (69% identical), SNORD3P1 (68% identical), U3 (68% identical), SNORD3E (68% identical), SNORD3G (68% identical), U3 (67% identical), U3 (66% identical), U3 (65% identical), U3 (64% identical), U3 (63% identical), U3 (62% identical), and 8 more.